GPR55 (G protein-coupled receptor 55)
Diseases named in the same sentence as GPR55 in open-access papers (continued):
Sharing a sentence is not in itself a finding about the gene and the disease.
tumor (continued). "We might speculate that the reduction of the levels of LPI in the tumour environment and consequently, reduced activation of GPR55 might contribute to observed effects." (PMID 31378204, 2019). "Based on this hypothesis, the present study was designed to identify peptide ligands of GPR55 for targeting tumor cells that express this receptor, which would potentially be useful for diagnosis and therapy of proliferative diseases." (PMID 28029647, 2017). "A therapeutic effect might be derived upon peptide binding to GPR55 and the consequent modulation of its signaling, or upon targeted delivery to tumor cells of a chemotherapeutic agent carried by the peptide." (PMID 28029647, 2017). "In particular, expression levels of GPR55 correlate with tumor aggressiveness." (PMID 28029647, 2017). "Much of the research conducted thus far indicates that GPR55 promotes tumor formation." (PMID 29066974, 2017). "Peptide binders of GPR55 might represent a valuable tool for in-vivo monitoring of tumor cells and tumor-specific delivery of chemotherapeutic agents." (PMID 28029647, 2017). "This suggests that GPR55 promotes tumor growth and aggressiveness." (PMID 25926795, 2015). "Furthermore, this diversity might account in part for the individual responsiveness of tumor cells to GPR55 stimuli by cannabinoids." (PMID 37998380, 2023). "Together, our results provide evidence indicating that LPI and its receptor GPR55 could participate in the incorporation of MCs to sites of tumor growth and that GPR55 blockage could be considered a therapeutic strategy to inhibit the recruitment of MCs to solid tumors." (PMID 37047288, 2023). "Furthermore, this diversity might determine the outcome and the individual responsiveness of tumor cells to GPR55 stimulation by cannabin oids." (PMID 37998380, 2023). "In addition, GPR55 enhanced skin cancer cell anchorage-independent growth, invasiveness and tumorigenicity in vivo, suggesting that it may promote not only tumor development, but also tumor aggressiveness." (PMID 30845666, 2019). "Moreover, due to the overexpression of this receptor in specific tumors, compounds that specifically bind GPR55 might represent valuable tools as tumor-targeting agents for delivery of classical chemotherapeutic drugs." (PMID 31214034, 2019). "Therefore, we cannot exclude the possibility that these candidate targets for miR-675-5p besides GPR55 could mediate tumor-suppressive function of miR-675-5p." (PMID 25889562, 2015). "The differential expression of GPR55 and PINK1 in tumor versus normal tissues further supports their potential as biomarkers and therapeutic targets." (PMID 40565152, 2025). "While the anti‐tumor potential of cannabinoids in GBM has traditionally been attributed to the modulation of ECS receptors, the roles of GPR55 and TRPV1 have also been the focus of recent investigation." (PMID 40781861, 2025). "Next to KPCY and KPCY55 tumor cells, we identified GPR55 in numerous immune cells of the TME (CD4+ and CD8+ T cells, macrophages, and CD11b+ myeloid cells) indicating a role for GPR55 in immune cell functions, such as migration and cytokine release." (PMID 39885986, 2024). "Although similar changes in tumor weight and volume were measured for KPCY and KPCY55 tumor-bearing GPR55 KO mice, we observed differences in the composition of their immune TME." (PMID 39885986, 2024). "GPR55 mRNA colocalized with KPCY55 tumor cells by 43.4% ± 13.4%, and with KPCY tumor cells by 31.9% ± 11% (all data are means ± SD)." (PMID 39885986, 2024). "We analyzed its correlation with age, sex, histological grade, TNM stage, and tumor status, and the dot plots showed that the expression of GPR55 mRNA was higher in HCC individuals with TNM I/II stage, and in tumor-free individuals." (PMID 37688769, 2023). "The G protein-coupled receptor 55 (GPR55), a lysophosphatidylinositol (LPI) receptor, has recently emerged as a potential new target for anti-tumor therapy." (PMID 37688769, 2023).
tumor (continued). "The xenograft model results suggested the contribution of SPL and glyceroLPLs to tumour progression depending on levels of SPL and GPR55." (PMID 36125914, 2022). "G protein-coupled receptor 55 (GPR55) probably plays a role in innate immunity and tumor immunosurveillance through its effect on immune cells, such as T cells and NK cells." (PMID 35562947, 2022). "Overexpression of miR-675-5p inhibits tumor growth, proliferation, migration, and invasion of NSCLC cells in vivo and in vitro, by targeting GPR55." (PMID 36291926, 2022). "The results from studies utilizing PANC-1 cell cultures are consistent with the tumor-derived data and indicate that the bifunctional properties of (R,S′)-MNF as GPR55 antagonist and β2-AR-biased agonist both contribute to the observed antitumor effects." (PMID 35256673, 2022). "The explanation for the observed improvement is most likely that GPR55 is a marker for T cells and B cells in lymph nodes, whereas CEA, CXCL16 and CXCL17, are markers for tumor cells of epithelial origin." (PMID 35562947, 2022). "Most evidence has consistently shown that GPR55 is activated by the endogenous phospholipid L-α-lysophosphatidylinositol (LPI), and a crucial role of LPI in tumor progression was postulated." (PMID 33802282, 2021). "GPR55 can increase proinflammatory molecules such as COX-2 and STAT3, which can assist in tumor initiation and progression." (PMID 34503163, 2021). "Peptide-P1 was also shown to inhibit GPR55-dependent proliferation of EHEB and DeFew cells, which are two human B-lymphoblastoid cell lines, and among other tumour cells, leukemic cells can metastasise at the bone level." (PMID 33902596, 2021). "Specifically, LPI activity has shown to be mediated by the interaction with the G protein-coupled receptor 55 (GPR-55), a cannabinoid receptor also described as correlated to tumor growth and aggressiveness." (PMID 29653539, 2018). "In response to the tumor microenvironment, LPI and GPR55 play a role in the modulation of migration, orientation and polarization of breast cancer cells." (PMID 25926795, 2015). "For example, GPR55 promotes tumor cell proliferation and angiogenesis, CB1 inhibits tumor growth and CB2 likely promotes tumor-tolerant immune cells." (PMID 25594019, 2014). "Immunohistochemical analysis revealed that PINK1 was expressed in 65% of tumor samples (13 positive and 7 negative), while GPR55 exhibited high expression in 95% of cases (19 positive and 1 negative)." (PMID 40565152, 2025). "GPR55 is a G-protein-coupled receptor (GPCR) whose activation by anandamide, 2-arachidonoylglycerol (2-AG) or lysophosphatidylinositol (LPI) as the main ligands resulted in higher tumor cell aggressiveness." (PMID 40434517, 2025). "In particular, the non-canonical CBR GPR55 has been shown to trigger intracellular calcium mobilization, which plays a key role in tumor progression." (PMID 40434517, 2025). "However, by measuring Ki-67 mRNA in KPCY55 tumor cells of ISH sections, we observed lower expression in GPR55 KO vs. WT mice." (PMID 39885986, 2024). "A CXCR3/CXCL9/CXCL10 axis could drive T cell infiltration into KPCY55 tumors of GPR55 KO mice, suggesting that GPR55 suppresses this pathway in PDAC, thereby promoting tumor growth." (PMID 39885986, 2024). "As a negative tumor regulator, we investigated the effects of GPR55 on the stimulation of the MAPK signaling pathway." (PMID 37688769, 2023). "On the other hand, GPR55 emerges as a central molecule mediating LPI-induced migration and actin cytoskeleton remodeling in MCs, which places that receptor as an attractive target to inhibit the recruitment of MCs to tumor niches." (PMID 37047288, 2023).
tumor (continued). "CC tumor cells contribute only marginally or not at all to GPR55 mRNA, depending on which subtype of tumor cells constitute the disseminated tumor cells in the node." (PMID 35562947, 2022). "The absence of GPR55 resulted in a lower concentration of the anti-tumour myeloid-derived tumour suppressing cells (MDSCs)." (PMID 35204820, 2022). "While the in vitro effects are promising, GPR55 inhibition does not directly translate to single agent efficacy in PDAC tumor models." (PMID 35256673, 2022). "Whether the low levels of GPR55 found in CC cell lines HT29 and T84 are derived from goblet-cell-like tumor cells is an open question." (PMID 35562947, 2022). "Moreover, the mRNA level of GPR55, which is known as a receptor of LPI, was higher in the tumour tissues than in the non‐tumour tissues." (PMID 36125914, 2022). "Although GPR55 transcript levels were higher in the estrogen-independent Type 2 EC tumours (n = 6), this was not statistically significant." (PMID 34324032, 2021). "GPR55 mRNA levels were decreased in nontumor exposed tissues and elevated in tumor lesions, compared to healthy controls." (PMID 34503163, 2021). "In these models, CB1 was up-regulated in inflamed non-tumor tissue and down-regulated in tumor lesions, while GPR55 was found to be regulated exactly in an inverse manner, acting oppositely to CB1." (PMID 31979368, 2020). "Experiments in cultured T98G cells suggested that this effect was mediated by the formation of a functional dimeric complex between GPR55 and CB2 receptors such that low concentrations of Δ9-THC activated the CB2 receptor and Erk expression thereby promoting tumor cell growth." (PMID 27774065, 2016). "However, in the presence of high Δ9-THC concentrations, Δ9-THC inhibited GPR55 which blocked the CB2 receptor and Erk activation thereby inhibiting tumor cell growth." (PMID 27774065, 2016). "miR-675-5p functions as a novel tumor suppressor in NSCLC and the anti-oncogenic activity may involve its inhibition of the target gene GPR55." (PMID 25889562, 2015). "The dysregulation of both ‘classical’ (CB1 and CB2) and ‘non-classical’ (TRPV1 and GPR55) endocannabinoid receptors in EC may provide insights into the variable effects of endocannabinoids observed in different tumour models." (PMID 40243844, 2025). "Spleen from healthy GPR55 KO mice do not show increased levels of CD3+ T cells as compared to healthy WT mice indicating that the regulation of the immune cell profiles were tumor specific." (PMID 39885986, 2024). "Notably, when comparing isotype control and anti-PD-1 antibody treatment, we observed that tumor volume and mass increased in WT, but not in GPR55 KO mice." (PMID 39885986, 2024). "As a result, we noticed differences in changes of tumor weight/volume that were greater between anti-PD-1-antibody-treated than isotype control-treated mice (p=0.07), suggesting that anti-PD-1 antibodies are more effective in KPCY55 tumors of GPR55 KO than WT mice." (PMID 39885986, 2024). "Notably, anti-PD-1 immunotherapy increased tumor burden in WT mice, while this effect was absent in the GPR55 KO mice." (PMID 39885986, 2024). "The treatment, however, did not further reduce tumor burden in GPR55 KO mice." (PMID 39885986, 2024). "Importantly, we observed that GPR55 was present in several types of immune cells of the TME, suggesting that GPR55 may influence tumor growth via actions of these cells." (PMID 39885986, 2024). "Interestingly, anti-PD-1 antibody treatment increased the tumor burden in WT, but not GPR55 KO mice." (PMID 39885986, 2024). "A correlation between Gβγ signaling and GPR55 has so far not been demonstrated in tumor cells." (PMID 37998380, 2023). "However, the lack of humanized monoclonal antibodies against GPR55 led us to develop peptide binders of this receptor for specific targeting of GPR55-positive tumor cells." (PMID 28029647, 2017).
tumor (continued). "Tumor cell-derived GPR55 does not seem to play a role in the differences seen in tumor burden between GPR55 KO and WT mice, but we cannot exclude that stromal TME cells like fibroblasts or endothelial cells, which are known to express GPR55, may contribute to it." (PMID 39885986, 2024). "Whether GPR55 has a physiological role in promoting positive prognosis or whether the positive effect is due to the fact that the biomarker reflects the absence of tumor cells is unclear." (PMID 35562947, 2022). "Total mRNA expression in KPCY55 tumor samples differs widely between GPR55 KO and WT mice, indicating the lack of GPR55 in cells of the TME, and the reduction of tumor cells in KO mice." (PMID 39885986, 2024). "As opposed to GPR55-/-, the CB1-/- knockout mice developed a higher number of tumors, with larger areas in different CRC models, i.e., spontaneous tumor progression and CAC." (PMID 34503163, 2021). "Furthermore, GPR55 antagonists CID and CBD did not affect proliferation of GBM cells after 24 h, although an inhibition of tumor cell proliferation of the pancreatic cell line PANC1 with both GPR55 antagonists was already reported." (PMID 33802282, 2021). "Because GPR55 appears to be predominantly expressed in immune cells and not in CC tumor cells, whereas CEA is expressed in CC tumor cells but not in immune cells, we investigated whether calculating the GPR55 mRNA/CEA mRNA ratios would sharpen the difference between TNM stages of CC patients." (PMID 35562947, 2022). "In this study, we added further insights into THC anti-tumor action, showing its ability to modify the number of Ki67+ cells of human patient-derived GBM cells, particularly through the activation of the orphan receptor GPR55 without affecting CB1 and CB2 receptors as usual targets." (PMID 33802282, 2021).
metabolic disease (8 papers, 2016 to 2025). A congenital disorder (due to inherited enzyme abnormality) or acquired (due to failure of a metabolically important organ) disorder resulting from an abnormal metabolic process. "This review will focus on the production and signalling pathways downstream LPI and the emerging evidence suggesting its role in metabolism, with specific interest in LPI, and its main receptor GPR55 involvement in metabolic diseases." (PMID 26784247, 2016). "In this review, we will focus on the physiological and pathophysiological roles of the lysophospholipid mediator lysophosphatidylinositol (LPI) and its receptor G-protein coupled receptor 55 (GPR55) in metabolic diseases." (PMID 26784247, 2016).
inflammation (6 papers, 2018 to 2025). Aberrant reaction of the microcirculation characterized by movement of fluid and leukocytes from the blood into extravascular tissues. "In a rat model of acute joint inflammation, the administration of O-1602, a GPR55 agonist, reduced nociception in a GPR55-dependent manner." (PMID 40429822, 2025). "Interestingly, GPR55-/- knockout mice in a DSS-induced mouse model of intestinal inflammation revealed rodents had less intensive response than wild-type mice, clearly indicating a pro-inflammatory role for GPR55 in intestinal inflammation." (PMID 35003109, 2021). "The GPR55 inhibitor CID16020046 reduced TNF-α, IL-1β, IL-6, and COX-2 levels in a mouse model of intestinal inflammation." (PMID 30453998, 2018).
neurodegenerative disease (6 papers, 2018 to 2024). A disorder of the central nervous system characterized by gradual and progressive loss of neural tissue and neurologic function. "In this sense, it is important to note that the association of LPI/GPR55 with degenerative diseases displays growing relevance." (PMID 33167441, 2020). "Since growing evidence suggests association of oxidative stress with different neurodegenerative diseases, further research on these compounds and GPR55 might be beneficial in future therapy of those diseases." (PMID 34769094, 2021). "In the present study, we investigated the neuroprotective potential of VCE-006.1, a chromenopyrazole derivative with biased orthosteric and positive allosteric modulator activity at GPR55, in murine models of two neurodegenerative diseases." (PMID 34946726, 2021). "Since inflammation is one of the hallmarks of neurodegenerative diseases, targeting GPR55 might be a novel therapeutic approach for the treatment of neurodegenerative diseases like PD, AD, and MS." (PMID 38895631, 2024). "Next, we have investigated its neuroprotective profile in vitro (cell-based assays) and in vivo (neurotoxin-based models or genetically-modified mice) models of two neurodegenerative diseases, PD and ALS, in which the potential of GPR55 as a neuroprotective target has been claimed." (PMID 34946726, 2021).
neurological diseases (4 papers, 2018 to 2025). "Currently, there are limited studies directly linking perinatal programming to alterations in Gpr55 expression and its role in the pathogenesis of neurological diseases." (PMID 41303637, 2025). "GPR55 antagonists have also been shown to have anti-neuroinflammatory properties in microglial cells, suggesting a possible treatment path for neurological disorders characterized by neuroinflammation." (PMID 38895631, 2024). "Research has revealed the structure-activity relationship of GPR55 with the selective antagonist CID16020046, while the antagonism of GPR55 has been proposed as an efficacious treatment for several neurological diseases." (PMID 36120297, 2022). "Among these receptors, the role of GPR55 in the perspective of neurological diseases and in microglia activation is controversial." (PMID 30453998, 2018).
bone disorder (3 papers, 2021 to 2025). "However, data concerning the involvement of GPR55 in bone metabolism are too few to fully understand the importance of this receptor in the onset and progression of skeletal diseases." (PMID 39940911, 2025). "Another study found that CBD and other GPR55 antagonists can inhibit bone resorption in vivo; additionally, GPR55 ligands affect osteoclast formation in vitro, suggesting a potential therapeutic role for CBD and minor cannabinoids in bone disorders." (PMID 37760233, 2023).
cardiovascular diseases (3 papers, 2015 to 2025). "Nonetheless, this pathway cannot be completely defined, and more studies are needed to determine the role of GPR55 in cardiovascular diseases and its therapeutic potential with cannabidiol inhibition." (PMID 40562493, 2025).
infection (2 papers, 2021 to 2023). The state of being infected such as from the introduction of a foreign agent such as serum, vaccine, antigenic substance or organism. "For instance, the expression of GPR55 increased in primary resting B lymphocytes and in monocyte-derived dendritic cells upon infection with Epstein–Barr virus and live Mycobacterium tuberculosis, respectively." (PMID 34948125, 2021).
animal disease (1 paper, 2024). "The potential of GPR55 agonists and antagonists is the subject of research in the modulation of inflammation and behavioral aberrations in animal disease models." (PMID 38931342, 2024).
immune disorders (1 paper, 2023). "The Gpr55 agonist O-1602 was shown to modulate pain and inflammation in immune disorders." (PMID 37645248, 2023).
intestinal disease (1 paper, 2022). "The mRNA expression level of GPR55 was determined in 382 regional lymph nodes from 121 CC patients representing all four TNM stages and in 77 lymph nodes from 13 patients with non-cancerous intestinal disease." (PMID 35562947, 2022).
peripheral neuropathy (1 paper, 2025). A disorder affecting the peripheral nervous system. "Our current therapeutic interest is in the development of the novel cannabinoid KLS-13019 as a GPR55 antagonist that can prevent and reverse chemotherapy-induced peripheral neuropathy (CIPN)." (PMID 39866868, 2025).